TTR (transthyretin)
Description:
Thyroid hormone-binding protein. Probably transports thyroxine from the bloodstream to the brain.
Synonyms: PALB; HsT2651; CTS; AMYLD1; ATTR; CTS1; HEL111; TBPA; TTN
Tractability: Small molecule: an approved drug acts on it; a structure with a bound ligand is known; a high-quality ligand is known; it has a high-quality binding pocket; it belongs to a druggable protein family. Antibody: its Gene Ontology location is reachable by antibodies, with high confidence; UniProt places it where antibodies can reach, with medium confidence; UniProt predicts a signal peptide or a membrane-spanning region. PROTAC: its protein half-life has been measured; a small molecule that binds it is known. Other modalities: an approved drug acts on it.
Target class: Secreted protein
Safety:
Unwanted effects reported when the protein is acted on. In parentheses: how it was acted on, where the effect was seen, and who reports it.
Cognitive Function, Decreased (serum; source: AOP-Wiki)
Gene: Protein-coding gene on chromosome 18 (31,557,009 to 31,606,585, forward strand). Ensembl gene ENSG00000118271.
Subcellular location: Secreted; Cytoplasm
Subcellular location (Human Protein Atlas): Golgi apparatus; Predicted to be secreted
Pathways (Reactome):
Sensory Perception: Retinoid metabolism and transport; The canonical retinoid cycle in rods (twilight vision)
Disease: Defective visual phototransduction due to STRA6 loss of function
Extracellular matrix organization: Non-integrin membrane-ECM interactions
Immune System: Neutrophil degranulation
Metabolism of proteins: Amyloid fiber formation
Gene Ontology:
Molecular function: identical protein binding; protein binding; molecular sequestering activity; hormone binding; protein-containing complex binding
Biological process: purine nucleobase metabolic process; retinoid metabolic process
Cellular component: extracellular exosome; extracellular region; azurophil granule lumen; cytoplasm; protein-containing complex
Genetic constraint (gnomAD): Loss-of-function variants: 9 observed, 14.97 expected, observed/expected ratio (o/e) 0.6, 90% interval 0.36 to 1.05. The upper end of that interval is the gene's LOEUF score, 1.05, which puts it in group 4 of 6, group 1 being the genes least tolerant of losing a copy. Missense variants: 135 observed, 194.16 expected, observed/expected ratio (o/e) 0.7, 90% interval 0.6 to 0.8. Synonymous variants: 75 observed, 75.75 expected, observed/expected ratio (o/e) 0.99, 90% interval 0.82 to 1.2.
Homologues: Orthologues: chimpanzee TTR (96% identical), rabbit TTR (86% identical), dog TTR (85% identical), rat Ttr (82% identical), macaque TTR (82% identical), mouse Ttr (82% identical), pig TTR (76% identical), guinea pig TTR (71% identical), tropical clawed frog ttr (57% identical), zebrafish ttr (50% identical), Caenorhabditis elegans R09H10.3 (22% identical), Drosophila melanogaster CG30016 (20% identical), and 1 more. Paralogues in human: URAD (15% identical).
Diseases named in the same sentence as TTR in open-access papers:
TTR is named in the same sentence as 468 diseases in open-access papers, as found by Europe PMC text mining. Sharing a sentence is not in itself a finding about the gene and the disease. The quoted sentences say what the papers report.
amyloidosis (1,140 papers, 2004 to 2026). A disorder characterized by the localized or diffuse accumulation of amyloid protein in various anatomic sites. "Transthyretin (TTR) amyloidosis involves TTR misfolding and aggregation, causing systemic organ dysfunction." (PMID 41492466, 2026). "The vast majority of cases of cardiac involvement (cardiac amyloidosis-CA) are due to immunoglobulin light chain (AL) amyloidosis, or transthyretin (ATTR) amyloidosis (either in its wild-type form-ATTRwt, or variant-ATTRv)." (PMID 42305910, 2026). "By substantially decreasing TTR production, vutrisiran aims to slow down or halt the progression of ATTRv amyloidosis, thus alleviating the debilitating symptoms associated with the deposition of amyloid fibrils throughout the body." (PMID 40943573, 2025). "Wild-type transthyretin amyloidosis (ATTRwt) is an age-associated systemic disorder characterized by extracellular deposition of misfolded transthyretin amyloid fibrils, leading to progressive organ dysfunction." (PMID 40613025, 2025). "Patients with transthyretin amyloidosis, both wild‐type and variant, exhibit elevated VE/VCO2 slopes, indicating ventilatory inefficiency." (PMID 40312148, 2025). "Asymptomatic individuals with a confirmed pathogenic mutation associated with variant transthyretin amyloidosis should undergo regular assessment to detect early signs of cardiac involvement." (PMID 40429539, 2025). "Hereditary transthyretin (ATTRv) amyloidosis is a rare but life-threatening multisystemic genetic disease associated with transthyretin (TTR) gene variants, of which the V30M (p.V50) and the V122I (p.V142I) variants are the most frequent." (PMID 40713704, 2025). "Transthyretin amyloid (ATTR) amyloidosis is a major systemic form of amyloidosis and the most common cause of cardiac involvement, which is, in turn, the leading cause of death in systemic amyloidosis." (PMID 40546628, 2025). "Hereditary amyloid transthyretin variant (ATTRv) amyloidosis is a rare, life-threatening disease, characterized by the deposition of aggregated transthyretin (TTR) protein in multiple organs and tissues." (PMID 40433205, 2025). "Over 150 transthyretin (TTR) mutations have been identified in hereditary transthyretin (ATTRv) amyloidosis, and new TTR variants have recently emerged." (PMID 40429804, 2025). "To conclude, the presented data expand the knowledge about the ATTRv amyloidosis landscape in Israel, indicate the populations at risk, and suggest that the spectrum of TTR variants in the Israeli population is broader than previously assumed." (PMID 39878313, 2025). "Another significant finding is the identification of the V122I variant in transthyretin (TTR) amyloidosis, first discovered in individuals of African ancestry." (PMID 39964583, 2025). "Recently, novel RNA‐targeted therapies have demonstrated effectiveness in treating PNP associated with amyloidosis, notably ATTRv amyloidosis, by curtailing abnormal protein formation and stabilizing the normal tetrameric structure of transthyretin." (PMID 40265689, 2025). "Genetic and clinical data of TTR variant carriers and ATTRv amyloidosis patients were collected from a national referral clinic and other subspecialty clinics in Israel." (PMID 39878313, 2025). "Recent studies suggest that the incidence of wild-type transthyretin amyloidosis is rising, likely due to improved diagnostic techniques and an aging population." (PMID 40448354, 2025). "ATTR-CM is a form of amyloidosis caused by the deposition of misfolding and aggregation of TTR protein in the cardiac tissue." (PMID 40056371, 2025). "We chose two clinically relevant, pathogenic mutations in TTR (Thr80Ala) and ASS1 (frameshift at the Phe150, “Phe150fs”) genes, causing hereditary amyloid transthyretin and type I citrullinemia, respectively." (PMID 40498069, 2025).
amyloidosis (continued). "Amyloid cardiomyopathy is mainly caused by two main subtypes of amyloidosis; immunoglobulin light chains amyloid‐cardiomyopathy (AL‐CM) and transthyretin amyloid‐cardiomyopathy (TTR‐CM)." (PMID 39873364, 2025). "In this study, we report a novel TTR variant (V121A) identified in two unrelated amyloidosis patients aged > 60 years who developed cardiomyopathy." (PMID 40429804, 2025). "TTR G83R represents a distinct mutation type that can induce vitreous amyloidosis, although the precise molecular mechanisms underlying its amyloid fibril formation remain incompletely understood." (PMID 40666113, 2025). "Another notable example is patisiran, an FDA-approved siRNA therapy for patients with hereditary transthyretin-mediated (hATTR; MIM 105210) amyloidosis, a progressive cardiomyopathy caused by heterozygous mutations in the TTR gene." (PMID 41244709, 2025). "transthyretin-mediated familial amyloid polyneuropathy (ATTR-PN), caused by TTR gene mutations, leads to systemic amyloid deposition and multisystem dysfunction." (PMID 41388420, 2025). "Previous studies about ATTRv amyloidosis in Israel focused on the Ser77Tyr variant, and less attention has been paid to other disease‐causing variants in TTR." (PMID 39878313, 2025). "Some individuals are especially susceptible to TTR amyloidosis because they inherited mutations in the transthyretin gene and the expressed TTR variants are less stable." (PMID 40367241, 2025). "This review summarizes the molecular mechanisms of ER-regulated TTR secretion and explores potential causes of ocular amyloid deposition, aiming to provide mechanistic insights into familial vitreous amyloidosis." (PMID 40666113, 2025). "The population attributable fraction, e.g. proportion of population with heart failure and amyloidosis due to pathogenic TTR variants in AGD35k, was 1.01% and 12.65% respectively." (PMID 41282679, 2025). "It is most commonly associated with light-chain (AL) amyloidosis and transthyretin (ATTR) amyloidosis, either hereditary or wild-type." (PMID 40427056, 2025). "Transthyretin-related (ATTR) amyloidosis is a progressive, multisystem disease caused by the extracellular deposition of misfolded transthyretin (TTR) monomers as insoluble amyloid fibrils." (PMID 40649158, 2025). "In this study, we present comprehensive genetic and clinical characterization of three cases of HCM mimics, including amyloidosis, Fabry disease (FD), and desminopathy caused by TTR p.V50M, GLA p.N215S, and DES p.R355* PNVs, respectively." (PMID 40574817, 2025). "Transthyretin-associated (ATTR) amyloidosis is one of the leading causes of cardiac amyloidosis (CA), a condition whose occurrence is due to either genetic ATTR mutations or the misfolding of the wild-type transthyretin (ATTRwt) protein." (PMID 40507472, 2025). "In TTR-related amyloidosis, the mechanisms underlying the kinetic instability and monomerization of the native TTR protein, leading to denaturation and misassembly with deposits of amyloid fibrils, are only partially understood." (PMID 39963604, 2025). "TTR amyloidosis (ATTR) can be classified into acquired (wild type [ATTRwt]) or hereditary (variant [ATTRv]) based on the presence of genetic mutations in the TTR gene." (PMID 40232627, 2025). "One current target is transthyretin, which causes amyloidosis, with CRISPR-Cas9 delivered as mRNA LNPs." (PMID 40880534, 2025). "Hereditary transthyretin (ATTRv) amyloidosis is a rare, intractable genetic disorder caused by mutations in the transthyretin (TTR) gene." (PMID 40898332, 2025). "Familial forms of amyloidosis, such as those caused by mutation of the transthyretin (TTR) gene, are characterized by autonomic SFN, as well as large-fiber involvement." (PMID 40002491, 2025). "Hereditary transthyretin (ATTRv) amyloidosis is a rare, adult‐onset autosomal‐dominant disorder caused by pathogenic variants in the transthyretin (TTR) gene." (PMID 39878313, 2025).
amyloidosis (continued). "The diversity of disease phenotypes associated with transthyretin (ATTR) amyloidosis poses challenges for measurement of health outcomes." (PMID 40299173, 2025). "Since TTR would normally sequester Aβ and prevent its aggregation, this reduction in TTR interferes with Aβ clearance and causes the increased amyloid deposition, notably in the hippocampus and cortex." (PMID 41013670, 2025). "Hereditary transthyretin (ATTRv) amyloidosis is a rare late‐onset multisystemic disorder, attributed to disease‐causing variants in the transthyretin (TTR) gene and inherited in an autosomal dominant manner." (PMID 39878313, 2025). "Of particular importance are parameters associated with progression of disease or predictive of mortality (New York Heart Association class, NT-proBNP levels, National Amyloidosis Centre stage, and serum transthyretin levels)." (PMID 39556242, 2025). "A 57-year-old Chinese male (167 cm, 59.3 kg, BMI 21.2 kg/m2) with a past medical history of well-controlled hypertension and hereditary transthyretin (TTR) amyloidosis (Ala117Ser mutation) was referred to our hospital." (PMID 40406766, 2025). "Variant transthyretin (ATTRv) amyloidosis is a rare, inherited disorder caused by mutations in the TTR gene, leading to amyloid fibril deposition." (PMID 40804349, 2025). "TTR amyloidosis (ATTR) can be hereditary in cases of misfolded mutated TTR (ATTR-v) or non-hereditary in cases of misfolded wild-type (wt) TTR (ATTR-wt)." (PMID 40565972, 2025). "Among the systemic forms of amyloidosis, immunoglobulin AL and transthyretin (ATTR) amyloidosis are the most commonly associated with thoracic manifestations of the disease." (PMID 40666562, 2025). "Although once thought to be restricted to endemic areas such as Portugal, Japan, and Sweden, ATTRv amyloidosis is now known to occur globally, with more than 150 pathogenic TTR mutations reported." (PMID 40898332, 2025). "Hereditary transthyretin (ATTRv) amyloidosis is a rare and fatal genetic disorder caused by mutations in the transthyretin (TTR) gene." (PMID 40898332, 2025). "Variant transthyretin (ATTRv) amyloidosis is a rare and life-threatening disease with roots tracing back several centuries." (PMID 40804349, 2025). "Today, both wild-type (ATTRwt) and variant (ATTRv) transthyretin amyloidosis are recognized and increasingly diagnosed." (PMID 40717228, 2025). "We report two unrelated patients with ATTRv amyloidosis and a novel V121A (p.V141A) variant in the TTR gene." (PMID 40429804, 2025). "One of the most notable examples of siRNA’s therapeutic potential is its application in treating transthyretin (TTR) amyloidosis, a rare and progressive disease caused by the accumulation of misfolded transthyretin protein." (PMID 39598489, 2024). "Worldwide, over 120 mutations in the TTR gene have been described, which cause familial transthyretin amyloidosis." (PMID 39768907, 2024). "The most common types of amyloidosis are light-chain amyloidosis (AL) and hereditary amyloidosis with mutations in the transthyretin gene (hATTR), with various phenotypes according to the mutation identified and age of onset." (PMID 39768907, 2024). "In fact, a study showed that proteolysis of TTR Ser52Pro, a variant that causes a severe form of amyloidosis, leads to the formation of a 49–127 fragment, which, when released in a physiological fluid agitation, quickly forms highly stable aggregates." (PMID 38907862, 2024). "Amyloid transthyretin (ATTR) amyloidosis can be due to pathogenic mutations in the TTR gene (variant ATTR, ATTRv) or be an age-related phenomenon (wild-type ATTR, ATTRwt)." (PMID 38308002, 2024). "Patients with transthyretin amyloidosis hold a mutation in the TTR gene that expresses a misfolded protein; the aberrant protein leads to amyloid fibrils, which lead to both peripheral neuropathy and cardiomyopathy." (PMID 38668084, 2024).
amyloidosis (continued). "ATTR-amyloidosis is primarily a result of wild-type (ATTRwt) or mutated (ATTRh) transthyretin protein deposition in the heart, while AL-amyloidosis is associated with the deposition of immunoglobulin light chains [3•]." (PMID 38809394, 2024). "All patients with ATTR-CA underwent additional genotyping to further analyze the underlying cause of ATTR-CA, revealing 17 patients with wild-type transthyretin amyloidosis (ATTRwt) and 6 patients with variant transthyretin amyloidosis (ATTRv)." (PMID 38224373, 2024). "The L55P mutation has been linked to increased aggregation of TTR,and hTTR tetramers with L55P subunits are presumed to be disease statesthat accelerate amyloidosis." (PMID 39057193, 2024). "Hereditary transthyretin (ATTRv) amyloidosis is a disease typically manifesting in adulthood, subsequent to mutations within the transthyretin (TTR) gene." (PMID 39286810, 2024). "Tafamidis has shown efficacy in a randomized trial in patients with wild-type transthyretin and variant transthyretin amyloidosis with cardiomyopathy." (PMID 39139790, 2024). "Transthyretin (ATTR) amyloidosis is a serious disease caused by misfolded TTR protein tissue buildup." (PMID 39726634, 2024). "CTS can be considered a prognostic marker in TTR-related amyloidosis and an additional risk factor for cardiac amyloidosis, irrespective of cardiac involvement." (PMID 38248075, 2024). "Variant transthyretin amyloidosis (ATTRv) is a rare multisystemic disorder caused by mutations in the transthyretin (TTR) gene." (PMID 39242501, 2024). "Amyloid neuropathy is a neurological complication of amyloidosis, mainly caused by the deposition of light chain or mutant transthyretin amyloid fibrils." (PMID 38893695, 2024). "Hereditary transthyretin (ATTRv, v for variant) amyloidosis is a rare, progressive and ultimately lethal autosomal dominant disorder." (PMID 38622453, 2024). "Patients with transthyretin amyloidosis were treated by delivering complexed with Cas9-encoding mRNA and a single guide RNA targeting transthyretin, resulting in an 87% reduction in serum transthyretin levels." (PMID 39030582, 2024). "Pericardial effusion is associated with amyloidosis, specifically amyloid light chain (AL) and transthyretin (ATTR) subtypes." (PMID 38465427, 2024). "These include transthyretin (TTR), which causes transthyretin amyloidosis (ATTR) in both familial/hereditary ATTR (variant ATTR [ATTRv]) and wild-type/non-hereditary (ATTRwt) forms, and light chains, which causes AL amyloidosis." (PMID 39092395, 2024). "Although studies have shown that more than 30 proteins have been identified to cause amyloidosis, only two, AL and TTR, are the most important." (PMID 39796004, 2024). "Noteworthy, a study on the penetrance of ATTR Val30Met amyloidosis on a Swedish cohort revealed a significant association between higher penetrance of the disease and maternal inheritance of the TTR variant." (PMID 38907862, 2024). "TTR-related amyloidosis is caused by systemic deposition of transthyretin, with clinical manifestations including neuropathy, cardiomyopathy, and oculoleptomeningeal involvement." (PMID 39138523, 2024). "Hereditary transthyretin (TTR) amyloidosis is a result of a genetic mutation that predisposes individuals to the instability of the tetrameric structure of transthyretin." (PMID 38248084, 2024). "Transthyretin amyloidosis is described as having a heterogeneous natural history, and therefore a poor prognosis, with a mean survival from diagnosis of 3.6 years for wild-type amyloidosis and 2.5 years for transthyretin amyloidosis of the Vall 122lle variant." (PMID 39449414, 2024). "Transthyretin (TTR) amyloidosis (ATTR) is a progressive, fatal disease caused by deposition of amyloid fibrils in different organs, leading to organ dysfunction and ultimately organ failure." (PMID 38673530, 2024).